GABRR3 (gamma-aminobutyric acid type A receptor subunit rho3)
Description:
Rho subunit of the pentameric ligand-gated chloride channels responsible for mediating the effects of gamma-aminobutyric acid (GABA), the major inhibitory neurotransmitter in the brain (By similarity). Rho-containing GABA-gated chloride channels are a subclass of GABA(A) receptors (GABAARs) entirely composed of rho subunits, where GABA molecules bind at the rho intersubunit interfaces (By similarity). When activated by GABA, rho-GABAARs selectively allow the flow of chloride anions across the cell membrane down their electrochemical gradient (By similarity).
Tractability: Small molecule: it belongs to a druggable protein family. Antibody: its Gene Ontology location is reachable by antibodies, with high confidence; UniProt places it where antibodies can reach, with medium confidence; UniProt predicts a signal peptide or a membrane-spanning region. PROTAC: a small molecule that binds it is known.
Gene: Protein-coding gene on chromosome 3 (97,985,102 to 98,035,315, reverse strand). Ensembl gene ENSG00000183185.
Subcellular location: Postsynaptic cell membrane; Cell membrane
Pathways (Reactome):
Neuronal System: GABA receptor activation
Gene Ontology:
Molecular function: GABA-A receptor activity; GABA-gated chloride ion channel activity; extracellular ligand-gated monoatomic ion channel activity; monoatomic ion channel activity; protein domain specific binding; transmembrane signaling receptor activity
Biological process: chemical synaptic transmission; chloride transmembrane transport; gamma-aminobutyric acid signaling pathway; synaptic transmission, GABAergic; monoatomic ion transmembrane transport; monoatomic ion transport
Cellular component: GABA-A receptor complex; GABA-ergic synapse; plasma membrane; membrane; postsynaptic membrane
Genetic constraint (gnomAD): Loss-of-function variants: 22 observed, 36.5 expected, observed/expected ratio (o/e) 0.6, 90% interval 0.43 to 0.86. The upper end of that interval is the gene's LOEUF score, 0.86, which puts it in group 3 of 6, group 1 being the genes least tolerant of losing a copy. Missense variants: 471 observed, 495.71 expected, observed/expected ratio (o/e) 0.95, 90% interval 0.88 to 1.02. Synonymous variants: 170 observed, 172.73 expected, observed/expected ratio (o/e) 0.98, 90% interval 0.87 to 1.12.
Homologues: Orthologues: chimpanzee GABRR3 (99% identical), macaque GABRR3 (97% identical), rabbit GABRR3 (85% identical), rat Gabrr3 (84% identical), mouse Gabrr3 (84% identical), guinea pig GABRR3 (81% identical), pig GABRR3 (79% identical), tropical clawed frog gabrr3 (72% identical), zebrafish gabrr3a (64% identical), zebrafish gabrr3b (64% identical). Paralogues in human: GABRR1 (60% identical), GABRR2 (59% identical), GABRB1 (37% identical), GABRB3 (36% identical), GABRB2 (36% identical), GABRP (31% identical), GLRA2 (31% identical), GABRQ (31% identical), GABRD (30% identical), GABRA6 (30% identical), GABRG1 (30% identical), GLRA3 (30% identical), and 33 more.
Diseases named in the same sentence as GABRR3 in open-access papers:
GABRR3 is named in the same sentence as 2 diseases in open-access papers, as found by Europe PMC text mining. Sharing a sentence is not in itself a finding about the gene and the disease.
GABRR3 shares sentences with these, for which no sentence is quoted: epilepsy (1 paper); Neurodevelopmental delay (1).